CCND1 (cyclin D1)
Diseases named in the same sentence as CCND1 in open-access papers (continued):
Sharing a sentence is not in itself a finding about the gene and the disease.
gastric cancer (continued). "Our data demonstrated that the reconstitution of TFF1 expression in gastric cancer cells abrogated H. pylori-induced activation of β-catenin and decreased mRNA and protein expression of c-myc and cyclin D1." (PMID 25980439, 2015). "MiR- 9 was reported to inhibit the proliferation, invasion, and metastasis of gastric cancer cells through downregulation of cyclin D1." (PMID 25971210, 2015). "CCND1 was found amplified in 19 of 109 (17.4%) gastric cancers, including 10 (9.2%) cancers with high-level amplification." (PMID 25649416, 2015). "The results showed that the expression of E2F1 was significantly decreased and the expression of cyclin D1 was also downregulated in gastric cancer cells transfected with pCDNA3.1-GAS5 compared to those with empty vector." (PMID 24884417, 2014). "Our previous study also reported that ShCCND1 significantly inhibited the expression levels of cyclin D1 and pRB, the major downstream molecule of cyclin D1, in another gastric cancer cell, AGS." (PMID 24618206, 2014). "Direct injection of Virus_CCND1 into gastric cancer would result in a downregulation of cyclin D1 not only in cancer cells but also in non-cancerous stromal cells." (PMID 24618206, 2014). "In vitro, the effect of silencing cyclin D1 on gastric cancer cell function, including cell proliferation, cell cycle, apoptosis, and cell motility was examined." (PMID 24618206, 2014). "We detected the downregulation of has-miR-9 in gastric cancer, which suppressed the proliferation, invasion, and metastasis of gastric cancer cells through targeting cyclin D1 and Ets1." (PMID 24982669, 2014). "The overexpression of cyclin D1 has been documented in a number of carcinomas, including gastric cancer." (PMID 24137325, 2013). "Ectopic expression or knockdown of miR-9 resulted in responsively altered expression of cyclin D1, Ets1 and their downstream targets phosphorylated retinoblastoma and matrix metalloproteinase 9 in cultured gastric cancer cell lines SGC-7901 and AGS." (PMID 23383271, 2013). "The increased levels of cyclin D1 expression induced by E2β were inhibited by PP2, indicating that c-Src iss involved in the induction of cyclin D1 expression induced by E2β in gastric cancer cells." (PMID 24137325, 2013). "In this study, we demonstrate, for the first time, that miR-9 directly targets cyclin D1 and v-ets erythroblastosis virus E26 oncogene homolog 1 (Ets1), and suppresses the proliferation, invasion and metastasis of gastric cancer cells in vitro and in vivo." (PMID 23383271, 2013). "There was an inverse correlation between miR-9 expression and cyclin D1 transcript levels in gastric cancer tissues (P<0.001)." (PMID 23383271, 2013). "To investigate the direct effects of miR-9 on the expression of cyclin D1 and Ets1 in gastric cancer cells, we performed the miRNA over-expression experiments." (PMID 23383271, 2013). "Lower miR-9 expression and higher transcript levels of cyclin D1 and Ets1 were observed in gastric cancer cell lines than those in normal gastric epithelial GES-1 cells." (PMID 23383271, 2013). "In this study, miR-9 was found to be down-regulated and inversely correlated with the expression of cyclin D1 and v-ets erythroblastosis virus E26 oncogene homolog 1 (Ets1) in gastric cancer tissues and cell lines." (PMID 23383271, 2013). "Next, the role of c-Src in the induction of cyclin D1 by estrogen was investigated in the gastric cancer cells." (PMID 24137325, 2013). "Lower miR-9 expression was observed in gastric cancer tissues with higher immunostaining of cyclin D1 (P<0.0001) or Ets1 (P<0.0001)." (PMID 23383271, 2013). "In contrast, higher cyclin D1 and Ets1 transcript levels were detected in gastric cancer tissues (P<0.0001 and P<0.0001, respectively)." (PMID 23383271, 2013). "In the present study, the underlying mechanisms by which ER-α36 functions in gastric cancer SGC7901 cells were investigated and the role of the c-src/cyclin D1 pathway was assessed." (PMID 24137325, 2013).
gastric cancer (continued). "Herein, CDH17 knockdown decreased β-catenin and GSK-3β phosphorylation, accompanied by a concomitant increase of Rb and reduction of Cyclin D1 in gastric cancer." (PMID 23554857, 2013). "The clinical significance of cyclin D1 overexpression in gastric cancer is inconclusive; it has been demonstrated to be associated with poor differentiation, diffuse type lesions, signet ring cell carcinoma or lymph node involvement, and depth of invasion." (PMID 23420289, 2013). "The results showed that RhoC, IQGAP1 and the C-terminal fragment of IQGAP1 significantly stimulated the proliferation of gastric cancer cells, and enhanced the expression of cyclin E and cyclin D1." (PMID 23145020, 2012). "We demonstrated that the expression level of cyclin D1 protein was reduced while p21 and p27 were markedly induced in gastric cancer cells transfected with pCDNA3.1-ZIC1 when compared to those pCDNA3.1 empty vector transfectants." (PMID 22799764, 2012). "ZIC1 can transcriptionally downregulate the Shh signaling and suppress the level of phospholated Akt and Erk, thus leads to the regulation of cell-cycle regulator kinases p21Waf1/Cip1, p27Kip1 and cyclin D1 in gastric cancer cells." (PMID 22799764, 2012). "We have observed that inhibition of Shh signaling by administration with cyclopamine suppresses AGS, BGC823 and SGC7901 gastric cancer cell migration, and regulates the expression of p21 and cyclin D1." (PMID 22799764, 2012). "The expression of P-glycoprotein, cyclin D1, p21 and p27 was detected in the gastric cancer cells using real-time PCR and western blot." (PMID 21569481, 2011). "We found that uterine cervical and small cell lung cancers were predicted to be RB-negative at high prevalence, while most uterine endometrial and stomach cancers were predicted to be RB1-positive by the CCND1/CDKN2A assay." (PMID 21447152, 2011). "We demonstrated that knockdown of CTGF expression significantly inhibited cell growth of gastric cancer cells and decreased cyclin D1 expression." (PMID 21955589, 2011). "This suggests that cyclin D1 overexpression is correlated with patient prognosis in gastric cancers." (PMID 20525401, 2010). "Cyclin D1 was previously studied in several series of gastric cancers, with a reported frequency of 20~56% of overexpression being reported, different from our results." (PMID 20525401, 2010). "Reduced KCNE2 expression was previously suggested to enhance proliferation in the gastric cancer cell line SGC7901 via increased expression of Cyclin D1." (PMID 20625512, 2010). "In fact, the ANOVA test only showed significant differences in mean frequencies of CCND1 gene positions between the groups ‘normal mucus' and ‘gastric cancer (p < 0.0001)." (PMID 21637674, 2009). "Esophageal and gastric cancers were chosen as models due to indications of increased gene amplification and over-expression of CCND1 and HER-2/neu sequences." (PMID 21637674, 2009). "Finally, LAT1 expression has been linked to chemoresistance in gastric cancer and cell cycle progression in pancreatic cancer through p38 MAPK activation and cyclin D1 suppression." (PMID 41487563, 2025). "Additionally, TACC3 can promote the EMT of gastric cancer cells through the ERK/Akt/cyclin D1 signaling pathway, which is a critical process in the metastasis of mesothelioma." (PMID 40223054, 2025). "Additionally, DDX21 directly enhances gastric cancer progression by increasing the mRNA and protein of cyclin D1 and CDK2." (PMID 39769343, 2024). "Studies have shown that the upregulation of hsaMrs2p regulates Mg2+ concentration by downregulating p27 and upregulating cyclin D1, while also inhibiting the release of mitochondrial cytochrome C, thereby conferring multiple drug resistance to gastric cancer cells." (PMID 38370477, 2024).
gastric cancer (continued). "In addition, Piezo1 knockdown induced G1 phase block in gastric cancer cells and downregulated phosphorylated Rb, Cyclin D1, CDK4, and CDK6, suggesting that Piezo1 is required for gastric cancer cell proliferation." (PMID 38690080, 2024). "Moreover, EXOSC5 expression has been linked to an increase in cyclin D1 and a decrease in p21/p27 expression, which promotes cell proliferation through the regulation of the AKT/STAT3 pathway in gastric cancer." (PMID 38164180, 2024). "Moreover, AZD1152, which specifically inhibits Aurora B, also inhibits Cyclin D1 to inhibit tumorigenesis and helps target gastric cancer." (PMID 36769170, 2023). "A circular endogenous RNA, has-circ00000647, interacts with and inhibits miR-326-3p and upregulates Cyclin D1 in gastric cancer cells (SGC-7901), showcasing another layer of gene expression regulation upstream of Cyclin D1 for the progression of gastric cancer." (PMID 36769170, 2023). "Cyclin D1 and Cyclin E1 expressions were compared for impact on survival for gastric cancer, and it was observed that Cyclin E-negative cancers portrayed good outcomes, while Cyclin E-positive cancers showed worse outcomes, as indicated through survival curves." (PMID 36769170, 2023). "A potential antitumor compound, Glycyrrhizic acid, has been tested for its efficacy in gastric cancer cell lines, and led to G1 arrest and induction of apoptosis, along with reduction of Cyclin D1, D2, D3, E1, and E2 and an increase in pro-apoptotic cleavage patterns of pro-caspases." (PMID 36769170, 2023). "Cyclin D1 and Cyclin E2 have been studied in the histopathological screening of gastric carcinoma." (PMID 36769170, 2023). "As a biomarker for predicting prognosis in gastric cancer, miRNA-194 may be utilized to target CCND1 and limit gastric cancer cell invasion and propagation." (PMID 36059797, 2022). "Furthermore, Mcl-1 knockdown also induces cell cycle arrest via decreasing cyclin D1, cell division cycle gene 2 (cdc2), and cyclin-dependent kinases 4/6 in gastric cancer." (PMID 35457012, 2022). "Subsequently, we also verified that terphenyllin could reduce the expression levels of proliferation-related protein c-Myc and cell cycle-related protein Cyclin D1, thus inhibiting the proliferation and blocking the cycle progression of gastric cancer cells." (PMID 35401187, 2022). "Gastric Cancer: curcumin lower the expression of human epidermal growth factor receptor 2 and the activity of p21-activated kinase 1, stop the transformation of stomach cancer cells from the G1 to S phase via the downregulation of cyclin D1." (PMID 36712505, 2022). "Moreover, METTL16-mediated m6A methylation boosted gastric cancer cell proliferation by increasing cyclin D1 expression." (PMID 36091006, 2022). "Collectively, our study further clarified that the antitumor effect of HOTAIR silencing in gastric cancer might resulted from the involvement of CCND1 and CCND2 medicated by miRNA‐206." (PMID 33473276, 2021). "Furthermore, we found that the Wnt/β-catenin target gene Cyclin D1, an oncogene, was downregulated in Mist1-overexpressing gastric cancer cells." (PMID 34149921, 2021). "For example, HOXD4 may promote proliferation by up-regulating c-Myc and cyclin D1 in gastric cancer cells." (PMID 35317110, 2021). "Further detection of the expression levels of CDK6 and Cyclin D1, which plays critical roles in cell cycle and is well known to be involved in the development of various types of human cancers including gastric cancer, showed downregulated expression induced by NDUFC1 knockdown." (PMID 34966665, 2021). "Cyclin D1 is frequently overexpressed in the early stages of gastric carcinomas." (PMID 34459131, 2021). "Additionally, we also assessed the role of AURKB kinase activity in the regulation of CCND1 transcription and related mechanism in promoting gastric cancer cell cycle progression and proliferation." (PMID 31982864, 2020).
gastric cancer (continued). "MiR-218 could suppress gastric cancer cell cycle progression at G1 phase through CDK6/Cyclin D1/E2F1 axis in a feedback loop." (PMID 33330110, 2020). "Accordingly, Rab11a could positively regulate cyclin D1 protein, suggesting Rab11a accelerated gastric cancer growth through induction of cell cycle regulators." (PMID 33178272, 2020). "In gastric cancer, overexpressed CORO1C is associated with poor prognosis and could promote metastasis by regulating cyclin D1 and vimentin." (PMID 32695668, 2020). "In this study, FAT4 repression increased cyclin D1, and cdk4 expression, promoting progression into the G1/S phase of the cell cycle, consistent with results obtained in a previous study on gastric cancer cells." (PMID 32366234, 2020). "Importantly, we found that high AURKB and CCND1 expression levels are correlated with shorter overall survival of gastric cancer patients." (PMID 31982864, 2020). "Furthermore, we show that AZD1152, a specific inhibitor of AURKB, can suppress the expression of CCND1 in the gastric cancer cells and inhibit cell proliferation in vitro and in vivo." (PMID 31982864, 2020). "Similarly, miR-107 has been found to increase the sensitivity of gastric cancer cells to oxaliplatin through inhibiting expression of P-gp, cyclin D1 and c-myc." (PMID 32192494, 2020). "Notably, we firstly identified CCND1 as a direct downstream target of AURKB that plays a key role in gastric cancer cell cycle and proliferation." (PMID 31982864, 2020). "Inhibition of WISP1 leads to decreases in cell proliferation, migration and invasion in gastric cancer cells via suppression of cyclin D1 and EMT progression, demonstrating that WISP1 could be an oncogene in gastric cancer." (PMID 30651114, 2019). "As cyclin D1 and vimentin play an oncogenic role in gastric cancer, CORO1C may exert its tumor‐promoting activity through these proteins." (PMID 30974047, 2019). "The CORO1C–Rac‐1–cyclin D1–vimentin pathway might also contribute to human gastric cancer and mediate the enhanced carcinogenicity of gastric cancer cells, which needs to be examined in future work." (PMID 30974047, 2019). "Therefore, high levels of cyclin D1 or vimentin indicated poor prognosis in gastric cancer patients." (PMID 30974047, 2019). "Additionally, it was also reported that dysfunction of cyclin D1 induces apoptosis of rat pheochromocytoma PC12 cells, and the expression level changes of cyclin D1 are related to apoptosis via G1 arrest of the cell cycle in gastric cancer cells." (PMID 30279365, 2018). "Cyclin D1 is frequently over-expressed in a substantial proportion of gastric cancer, and its expression may be governed by the ERK signaling." (PMID 30200948, 2018). "Cyclin D1 is expressed among genetic alterations in gastric carcinomas, including advanced gastric carcinomas and early stage, using immunohistochemistry as a good standard method for the detection of early stage gastric cancers and their differentiation from hyperplastic polyp patients." (PMID 29867026, 2018). "Interestingly, ZNRD1 was found to suppress CDK4, Cyclin D1, and p21 and inhibit the growth of gastric cancer and leukemia cells in vitro." (PMID 28052024, 2017). "It has also been reported that PAK5 might contribute to gain of tumor growth potential, acting by affecting the expression of Cyclin D1 in gastric cancer." (PMID 29041983, 2017). "Interestingly, Shao and colleagues found cyclin D1 and p16 expression in gastric cancer and normal tissues, respectively." (PMID 28567097, 2017). "We have previously confirmed that cyclin D1 is regulated by AEG‐1 in gastric cancer." (PMID 28661037, 2017). "In addition, Notch4 activation induced expression and activation of Wnt1, β-catenin and downstream target genes, c-Myc and cyclin D1, in gastric cancer cells, while Notch4 inhibition had opposite effects." (PMID 27363496, 2016).
gastric cancer (continued). "Here, we found that SAHA promoted acetylation of histones 3 and 4 in gastric cancer cells, which were recruited to the promoter of p21, p27, c-myc, Cyclin D1 and nanog for the up-regulated transcription of the former two and the down-regulated expression of the latter three." (PMID 27447743, 2016). "CCND1 amplification was observed in 19 of 109 gastric cancers (17.4%)." (PMID 25649416, 2015). "In summary, we showed that Lin28 could inhibit the expression of miR-107, thereby up-regulating C-myc, P-gp and down-regulating Cyclin D1, subsequently result in chemo-resistance of gastric cancer cells." (PMID 26636340, 2015). "Therefore, these experimental results suggest the possibility that lentivirus-mediated shRNA targeting of cyclin D1 can be used as a new gastric cancer therapy." (PMID 24618206, 2014). "In this study, we hypothesized that inhibition of cyclin D1 in human gastric cancer could suppress cancer progression in vitro and in vivo." (PMID 24618206, 2014). "Therefore, direct injection of lentivirus-mediated ShCCND1 is an efficient tool to significantly suppress cyclin D1 in gastric cancer cells." (PMID 24618206, 2014). "In conclusion, this CagA- PI3K/AKT-Sp1-RBP2-Cyclin D1 pathway may serve as a novel mechanism for gastric epithelial cell malignant transformation and then gastric cancer (GC)." (PMID 25015565, 2014). "Therefore, direct injection of Virus_CCND1 effectively inhibited gastric cancer growth due to growth inhibition by simultaneously blocking cancer cell and non-cancer cell growth." (PMID 24618206, 2014). "Taken together, these data suggest that targeting cyclin D1 with lentivirus-mediated ShCCDN1 could have an inhibition effect on cell proliferation and an induction effect of apoptosis in vivo on human gastric cancer." (PMID 24618206, 2014). "In addition, our data confirmed that miR-9 directly targeted cyclin D1 and Ets1 in gastric cancer cells through 3′-UTR luciferase reporter assay." (PMID 23383271, 2013). "This study extends our knowledge about the regulation of cyclin D1 and Ets1 at the post-transcriptional level by miRNA, and suggests that miR-9 may be of potential values as a novel therapeutic target for gastric cancer." (PMID 23383271, 2013). "As a result, in the SCG7901 and High36 cell lines, E2β upregulated the expression levels of cyclin D1, whereas in the Low36 cells, E2β failed to induce cyclin D1 expression, indicating that estrogen induces cyclin D1 expression via ER-α36 in gastric cancer cells." (PMID 24137325, 2013). "Furthermore, anti-miR-9 inhibitor promoted the proliferation, migration and invasion of gastric cancer cells, while knocking down of cyclin D1 or Ets1 partially phenocopied the effects of miR-9 over-expression." (PMID 23383271, 2013). "In addition, ER-α36-mediated estrogen signaling stimulated proliferation of the gastric cancer cells through the activation of the c-Src signaling pathway and the upregulation of cyclin D1 expression." (PMID 24137325, 2013). "Since above results indicated the negative regulation of cyclin D1 and Ets1 expression by miR-9, we hypothesized that knockdown of cyclin D1 and Ets1 might exert similar effects on cultured gastric cancer cells." (PMID 23383271, 2013). "The immunoreactivity of cyclin D1 and Ets1 was significantly higher in gastric cancer cases with deeper gastric wall invasion (P<0.001 and P = 0.001), lymph node metastasis (P<0.001 and P<0.001), distant metastasis (P<0.001 and P<0.001), and advanced TNM stage (P<0.001 and P = 0.004)." (PMID 23383271, 2013). "In this study, we demonstrated that over-expression of miR-9 attenuated the proliferation, migration and invasion of gastric cancer cells, which was similar to that of cyclin D1 or Ets1 knockdown, suggesting the potential application of miR-9 as a target for the therapeutics of gastric cancer." (PMID 23383271, 2013).